ST3GAL6 (ST3 beta-galactoside alpha-2,3-sialyltransferase 6)
Diseases named in the same sentence as ST3GAL6 in open-access papers (continued):
Sharing a sentence is not in itself a finding about the gene and the disease.
tumor (17 papers, 2012 to 2026). "From this 14-glycogene signature, overexpressed ST3GAL6 was further identified to be positively associated with tumor aggressiveness and poor prognosis in UBC patients, from both public datasets and our own cohorts." (PMID 32929335, 2020). "In tumor tissues, the expression of ST3GAL6 was found to be notably reduced, whereas the expression levels of B3GALT2, ABO FUT3, B3GNT3, and B3GNT5 were observed to be significantly elevated." (PMID 37781041, 2023). "In GSE73731 dataset (n = 256 in total), upregulated ST3GAL5 (p < 0.0001) and ST3GAL6 (p = 0.0099) was positively correlated only with tumor grade in ccRCC, respectively." (PMID 36172374, 2022). "Similar observations were made in urinary bladder cancer with a positive correlation between increased ST3GAL6 expression and tumor stage, grade as well as poor outcome." (PMID 34975914, 2021). "ST3GAL6-silenced MM cells displayed reduced homing and engraftment in vivo, with decreased tumor burden and prolonged survival." (PMID 33921986, 2021). "Different roles of the glycogene ST3GAL6 in different subtypes of UBC patients for tumor progression were indicated." (PMID 32929335, 2020). "Increased ST3GAL6 was positively correlated to tumor stage, grade, and survival in UBCs from public datasets or our cohort (n=52)." (PMID 32929335, 2020). "Targeting this peptide under non-treatment conditions could be a promising immunotherapeutic strategy, provided that the tumor relies on ST3GAL6 suppression and the generation of the RLSSSLPSR peptide as byproduct of this tumor promoting mechanism." (PMID 39835134, 2024). "ST3GAL6 was negatively associated with the subtype with luminal feature in UBC patients (n = 2130 in total) and increased ST3GAL6 expression was positively correlated to tumor stage, grade, and survival in UBCs (n = 52)." (PMID 33921986, 2021). "Furthermore, mice injected with ST3GAL6 knockdown MM cells demonstrated a decreased tumor burden and prolonged survival." (PMID 34975914, 2021). "Furthermore, successful knockdown of ST3GAL6 severely inhibited homing of MM cells to the BM and ST3GAL6 knockout MM cells showed decreased tumor burden in a murine model." (PMID 31143186, 2019). "Focusing on glycosyltransferases expression in tumor tissues, we observed two distinct expression clusters, segregating FUT3, FUT4, FUT6, and ST3GAL4 transcripts, from FUT7, FUT9, ST3GAL3, and ST3GAL6." (PMID 39508360, 2025). "To collect further evidence for the tumor specificity of the two cryptic peptides RVYLDIVTPK (IFT81) and RLSSSLPSR (ST3GAL6), we evaluated their immunogenicity applying an in vitro priming assay." (PMID 39835134, 2024). "In the tumor samples, F2, GLS2, IDO2, and PLAUR were shown to be significantly upregulated, while GNG7, PIK3CG, and ST3GAL6 were significantly down-regulated." (PMID 33619235, 2021). "However, ST3GAL6 expression did not exhibit significant correlations with tumor grade and tumor stage." (PMID 36172374, 2022). "Based on the expression profile of FPGT, ST3GAL6 and ADAM19 in SP gene signature list, we propose a probable mechanism, which may be active in the SP cells that accounts for the SP cell survival, differentiation and tumor maintenance in ovary." (PMID 22272227, 2012). "Based on these results and identification of these genes (FPGT, ST3GAL6 and ADAM19) in our SP gene list, we identified a potential mechanism, which may be active in the SP cells that accounts for the SP cell survival, differentiation and tumor maintenance in ovary." (PMID 22272227, 2012).
cancer (14 papers, 2012 to 2025). A tumor composed of atypical neoplastic, often pleomorphic cells that invade other tissues. "One example of a sialylation-related enzyme implicated in cancer development is ST3 beta-galactoside alpha-2,3-sialyltransferase 6 (ST3GAL6), which is essential for sialylated Lewis antigen synthesis." (PMID 39123480, 2024). "ST3GAL6 belongs to sialyltransferase family, involving in synthesis of glycolipid substrates, abnormalities of which are associated with cancer development, cell adhesion, invasion and metastasis." (PMID 37781041, 2023). "In vehicle-treated mice we found consistent upregulation of St3gal6, a sialyltransferase associated with immune cell trafficking and worse outcomes in different models of cancer, and Lrrc3, a leucine rich repeat containing protein." (PMID 34281628, 2021). "The Kaplan-Meier survival analysis showed that the ST3GAL6 expression level was inversely associated with OS in all 4 datasets (n=739 in total, p < 0.05) and disease-free/cancer-specific survival in all 3 datasets (n=707 in total, p < 0.05), respectively." (PMID 32929335, 2020). "Altogether, the tight positive regulation of lncRNA-ST3GAL6 on its host gene is elucidated in various cancer types, even if the function of ST3GAL6 in cancer cells is opposite." (PMID 36092699, 2022). "Such a discrepancy in the ST3GAL6-mediated signaling in different cancer cells probably can be elucidated by identification of its key downstream glycoproteins." (PMID 36092699, 2022). "ST3GAL6 is excessively expressed in different types of cancers." (PMID 37781041, 2023). "In this study, we found that the downregulation of ST3GAL6 predicts a poor prognosis in LUAD samples, reinforcing the notion that ST3GAL6 may play an oncogenic or tumor-suppressive role which is dependent on the cancer type." (PMID 36092699, 2022). "Since the activation of EGFR signaling may be involved in cancer cell invasion, we carried out a transwell assay and found that ST3GAL6 knockdown could significantly increase cancer cell invasiveness." (PMID 36092699, 2022). "Hence, it is necessary and intriguing to further identify the potential target glycoproteins of the ST3GAL6 protein in order to fully understand its role in various cancer types." (PMID 36092699, 2022). "The complicated role of ST3GAL6 in carcinogenesis is suggested; to explain such discrepancy, the accurate quantitative analysis method, precise application to clinical diagnosis and well characterization of the function and putative substrates of ST3GAL6 in each cancer type should be explored." (PMID 32929335, 2020). "However, the promoter of B4GALNT2 and ST3GAL6 seems to be hypermethylated in cancer in contrast to the MGAT3 promoter, which is hypomethylated." (PMID 27429195, 2016). "ADAM19, FPGT and ST3GAL6 were found to be over expressed in SP cells and may be potential cancer stem-like cell related genes." (PMID 22272227, 2012). "A total of 10 genes that were disrupted or within breakpoint‐associated TAD structures were classified as known (FHIT, FLCN, NCOA4, and RET) or candidate cancer genes (LLGL1, LRIG1, LYRM9, RASGEF1A, ST3GAL6, and TMEM199)." (PMID 31943436, 2020). "Analysis demonstrated two known cancer genes (NCOA4 and RET) and a further five candidate cancer genes (LLGL1, LRIG1, LYRM9, ST3GAL6, and TMEM199) were within breakpoint‐containing TADs." (PMID 31943436, 2020).
infection (2 papers, 2023 to 2024). The state of being infected such as from the introduction of a foreign agent such as serum, vaccine, antigenic substance or organism. "However, only the infection with G9P was associated with a significant downregulation of the expression of genes encoding ST3Gal (ST3Gal2, ST3Gal3, and ST3Gal6) and ST6Gal (ST6Gal1) sialyltransferases." (PMID 37515094, 2023). "Compared to mock-infected cells, AIV infection significantly upregulated the expression of ST3GAL6 and MGAT2 genes at 12-, 24-, 36-, and 48-hours post-infection, and ST3GAL1 gene at 24-, 36-, and 48-hours post-infection, while B4GALT1 expression remained largely unchanged." (PMID 39652582, 2024).
ST3GAL6 also shares sentences with these, for which no sentence is quoted: lung adenocarcinoma (2 papers); ovarian carcinoma (2); cutaneous melanoma (1); glioma (1); hematological malignancies (1); hypothyroidism (1); inflammation (1); inflammatory bowel disease (1); lymph node metastasis (1); membranous nephropathy (1); metastatic disease (1); non-small cell lung carcinoma (1); ovarian serous carcinoma (1); plasma cell disorders (1); rheumatoid arthritis (1); type 2 diabetes (1); uveal melanoma (1).